NEAT1 (nuclear paraspeckle assembly transcript 1)
Diseases named in the same sentence as NEAT1 in open-access papers (continued):
Sharing a sentence is not in itself a finding about the gene and the disease.
pneumonia (5 papers, 2019 to 2024). An acute, acute and chronic, or chronic inflammation focally or diffusely affecting the lung parenchyma, caused by an infection in one or both of the lungs (by bacteria, viruses, fungi, or mycoplasma.). "More compelling evidence on the role of NEAT-1 on the NLRP3 inflammasome activation surfaced in 2019 where NEAT-1 deficiency in peritonitis and pneumonia mouse models dramatically reduced the inflammatory responses." (PMID 33101288, 2020). "Moreover, in the mouse models of peritonitis and pneumonia, Neat1 deficiency significantly reduces inflammatory responses." (PMID 30940803, 2019). "NEAT1 can also activate inflammasomes in macrophages, promoting the development of peritonitis and pneumonia." (PMID 34972503, 2021). "Neat1+/+ and Neat1−/− mice were intranasally instilled with TurboFect reagent and flagellin to induce pneumonia." (PMID 30940803, 2019). "A study indicated that induction of pneumonia in human embryonic lung fibroblasts upregulated NEAT1 expression, while transfection with si‐NEAT1 could increase miR‐146b expression, thereby enhancing cell viability and reducing apoptosis." (PMID 38757482, 2024). "Furthermore, NEAT1 has been observed to be highly expressed in pneumonia, consistent with this study (p < 0.01)." (PMID 38757482, 2024). "NEAT1 facilitated inflammatory injury and apoptosis in pneumonia through TLR4/NF-κB signaling." (PMID 34672863, 2021). "To evaluate the role of Neat1 on NLRC4 inflammasome activation in vivo, we used a mouse model of flagellin-induced pneumonia." (PMID 30940803, 2019).
preeclampsia (5 papers, 2021 to 2025). Preeclampsia is a hypertensive disorder of pregnancy that is characterized by new-onset hypertension with proteinuria presenting after 20 weeks of gestation, and depending on mild or severe forms may initially present with severe headache, visual disturbances, and hyperreflexia. "This study aimed to study the correlation between preeclampsia (PE) and lncRNA nuclear paraspeckle assembly transcript 1 (NEAT1), and to examine the molecular mechanisms behind the development of PE." (PMID 38709402, 2024). "For instance, in preeclampsia, NEAT1 can inhibit trophoblast cell proliferation." (PMID 41268559, 2025).
type 2 diabetes (5 papers, 2022 to 2025). "In blood serum taken from Type 2 diabetes patients, increased expression in three lncRNAs, nuclear enriched abundant transcript 1 (NEAT1), metastasis-associated lung carcinoma transcript 1 (MALAT1/NEAT2), and NF-kappaB interacting lncRNA (NKILA), was observed." (PMID 36005827, 2022).
allergic rhinitis (4 papers, 2021 to 2025). Inflammation of the nasal mucous membranes caused by an IgE-mediated response to external allergens. "Circulating lnc‐NEAT1 and miR‐125a are aberrantly expressed and linked with Th2 cells and symptom severity in pediatric allergic rhinitis." (PMID 35064698, 2022). "Long noncoding RNA nuclear enriched abundant transcript 1 (lnc‐NEAT1) and its target microRNA‐125a (miR‐125a) are reported to regulate immune and inflammation process in allergic rhinitis (AR)." (PMID 35064698, 2022).
Arthritis (4 papers, 2020 to 2025). Inflammation of a joint. "In a type II collagen-induced arthritis mouse model, the in vivo injection of NEAT1 siRNA decreased the number of Th17 cells, thereby reducing the arthritis severity." (PMID 40362651, 2025). "Our results showed that the expression of NEAT1 is markedly elevated in patients who have skin lesions, neurological symptoms, vascular involvement, and articular involvement (arthritis)." (PMID 35127819, 2021). "The results of another study have shown that lncRNA NEAT1 is upregulated in PBMCs of patients with RA, and the therapeutic effective of depleted lncRNA NEAT1 on alleviating the inflammatory degree was confirmed in arthritis mouse models." (PMID 33042992, 2020). "Importantly, an in vivo experiment showed that NEAT1 knockdown reduces arthritis scores, making NEAT1 a promising potential therapeutic target." (PMID 39859276, 2025).
breast invasive carcinoma (4 papers, 2018 to 2022). "Previous study revealed that NEAT1 emerged as an important regulator in cancer development and was downregulated in invasive breast cancer, which was consistent with our results." (PMID 33494814, 2021).
diabetic cardiomyopathy (4 papers, 2021 to 2025). Diabetic cardiomyopathy is a disorder of the heart muscle in people with diabetes. "Previous studies have found that catalpol inhibits cardiomyocyte cell death via the Neat1/miR-140e5p/HDAC4 axis in diabetic cardiomyopathy." (PMID 36353492, 2022). "This study aimed to explore the efficacy of combination treatment with dendrobium mixture and metformin (Met) in diabetic cardiomyopathy (DCM) and its effects on NEAT1 and the Nrf2 signaling pathway." (PMID 34231706, 2021).
endothelial dysfunction (4 papers, 2020 to 2025). In vascular diseases, endothelial dysfunction is a systemic pathological state of the endothelium (the inner lining of blood vessels) and can be broadly defined as an imbalance between vasodilating and vasoconstricting substances produced by (or acting on) the endothelium. "NEAT1-formed ceRNA participates in endothelial dysfunction by regulating inflammation in vein graft failure." (PMID 35935642, 2022). "In conclusion, we constructed a lncRNA-associated ceRNA network based on the sequencing data and identified lncRNA NEAT1 is an essential fraction in endothelial dysfunction." (PMID 32148949, 2020). "Several published studies have shown that NEAT is upregulated in AS arteries, most of which demonstrated that NEAT1 was related to endothelial dysfunction and vascular inflammation in AS, but how NEAT1 regulates VSMC function in AS are not yet fully understood." (PMID 38646788, 2024). "Prior studies have shown that NEAT1 promotes endothelial pyroptosis and vascular inflammation through KLF4/NLRP3 signaling, and that exercise downregulates NEAT1 to attenuate endothelial dysfunction in AS." (PMID 41268533, 2025).
familial tumor syndrome (4 papers, 2022 to 2023). "LncRNA NEAT1 (NEAT1), encoding two variants of Neat1_v1 (3.7kb) and Neat1_v2 (23kb), is transcribed from a gene locus called multiple endocrine tumor type 1 in familial tumor syndrome on chromosome 11, which abnormally expressed in many malignant tumors, including CRC." (PMID 36262350, 2022). "For example, lncRNA nuclear paraspeckle assembly transcript 1 (NEAT1) is a multiple endocrine neoplasia type 1 locus (Chr 11q13.1) transcript that is involved in familial tumor syndromes." (PMID 38002356, 2023). "lncRNA NEAT1 was initially found in chromosome II of multiple secretory adenoma type I of familial tumor syndrome." (PMID 36185217, 2022).
fibrosis (4 papers, 2021 to 2023). the formation of excess fibrous connective tissue in an organ or tissue in a reparative or reactive process. "We also analyzed the expression of Neat1 and vimentin, a cardiac fibrosis marker, by immunofluorescence staining and found that Neat1 and vimentin were both upregulated in the areas with cardiac fibrosis." (PMID 34980170, 2022). "The lncRNA nuclear enriched abundant transcript 1 (Neat1) promotes cardiac fibrosis in HF through the increased recruitment of EZH2 to the Smad7 promoter region." (PMID 36552599, 2022). "The downregulation of NEAT1 and overexpression of miR-139-5p suppress the expression of profibrotic markers in murine fibrosis models via targeting β-catenin/SOX9/TGF-β1 pathway." (PMID 34531378, 2021). "All these results imply that Neat1 promotes cardiac fibrosis by recruiting EZH2, without affecting the EZH2 expression level." (PMID 34980170, 2022). "Another four studies revealed that the serum TGFB2/TGFB2-OT1, lnc-SPARCL1-1:2, lncRNA RABGAP1L-DT-206, MALAT1, Neat1, and HULC expression were significantly higher in patients with advanced fibrosis/cirrhosis (F = 3–4) than in those without it (F = 0–2)." (PMID 36979495, 2023).
infarction (4 papers, 2019 to 2020). A localised pathological necrosis of tissue resulting from obstruction of the blood supply usually by a thrombus, an embolus, or vascular torsion. "Several lncRNAs with a GC-AG intron were described to play a role in neuron development and growth like the MEG3 gene, the NEAT1 gene, the SOX2-OT gene, the GDNF-AS1 (GDNF antisense RNA 1) gene and the MIAT (myocardial infarction associated transcript)." (PMID 32499820, 2020). "This study also demonstrates that long non-coding RNAs are incorporated into vesicles and shuttled between cardiomyocytes and fibroblasts post-infarction and identifies an indispensable role for lncRNA Neat1 in cardiac fibroblasts." (PMID 31634682, 2019).
medulloblastoma (4 papers, 2022 to 2024). A malignant, invasive embryonal neoplasm arising from the cerebellum. "Taken together, these results clearly reveal an oncogenic role of NEAT1, which is positively associated with cisplatin resistance in medulloblastoma." (PMID 35313796, 2022). "In view of the positive association between NEAT1 and cisplatin resistance in medulloblastoma, we evaluated the underlying cellular mechanisms of the NEAT1-promoted cisplatin resistance." (PMID 35313796, 2022). "Overall, the current evidence indicates that HOTAIR, NEAT1, linc-NeD125, HHIP-AS1, CRNDE, and TP73-AS1 are oncogenic lncRNAs and Nkx2-2as is a tumor-suppressive lncRNA that forms lncRNA-associated ceRNAs in medulloblastoma." (PMID 39010056, 2024). "In medulloblastoma, lncRNA nuclear paraspeckle assembly transcript 1 (NEAT1) is upregulated and acts as an oncogene." (PMID 36499136, 2022). "Our study will provide new molecular mechanisms for the NEAT1-mediated cisplatin resistance of MB, contributing to the development of the lncRNA-based therapeutic approaches against chemoresistant medulloblastoma." (PMID 35313796, 2022). "Here, we demonstrated that NEAT1 was significantly overexpressed in medulloblastoma specimens compared to matched normal brain tissues, suggesting a positive association between NEAT1 and MB progression." (PMID 35313796, 2022). "Our study aimed to investigate the biological functions of NEAT1 in cisplatin-resistant medulloblastoma." (PMID 35313796, 2022). "To explore the clinical roles of lncRNA NEAT1 in medulloblastoma, we analyzed the NEAT1 expressions in 40 cases of medulloblastoma patients and adjacent tissues using qRT-PCR." (PMID 35313796, 2022). "The transcription level of NEAT1 was significantly increased in MB tissues compared with the paired noncancerous tissues, suggesting NEAT1 plays an oncogenic role in medulloblastoma." (PMID 35313796, 2022). "HOTAIR, NEAT1, linc-NeD125, HHIP-AS1, CRNDE, and TP73-AS1 are the oncogenic lncRNAs, and Nkx2-2as is a tumor-suppressive lncRNA that develop lncRNA-associated ceRNA networks in medulloblastoma." (PMID 39010056, 2024). "This chemoresistance of medulloblastoma cells is mediated via the NEAT1/miR-23a-3p/GLS axis." (PMID 39010056, 2024). "We report that NEAT1 was significantly upregulated in medulloblastoma patient specimens." (PMID 35313796, 2022). "We then evaluated the relevance of miR-23a-3p and NEAT1 in medulloblastoma." (PMID 35313796, 2022). "We further examined the roles of NEAT1 in cisplatin sensitivity of medulloblastoma cells." (PMID 35313796, 2022). "However, the roles and precise mechanisms of NEAT1 in regulating glutamine metabolism in chemosensitivity of medulloblastoma remain unclear." (PMID 35313796, 2022). "HOTAIR, NEAT1, linc-NeD125, HHIP-AS1, CRNDE, and TP73-AS1 are the identified oncogenic lncRNA in medulloblastoma, and Nkx2-2as is a tumor-suppressive lncRNA in medulloblastoma." (PMID 39010056, 2024). "NEAT1 elevates GLS1 expression and glutamine metabolism in medulloblastoma cells by targeting miR-23a-3p." (PMID 36499136, 2022). "Mechanically, NEAT1 sponges miR-23a-3p to form a ceRNA network to regulate expression of the miR-23a-3p target, GLS, leading to cisplatin resistance in medulloblastoma." (PMID 35313796, 2022). "However, the biological roles of lncRNA NEAT1 in medulloblastoma have not been unveiled." (PMID 35313796, 2022).
non-alcoholic fatty liver disease (4 papers, 2020 to 2024). "More importantly, NEAT1 plays an important role in a rat model of non-alcoholic fatty liver disease (NAFLD) involving the mammalian target of rapamycin/S6 kinase beta-1 signaling pathway." (PMID 33574830, 2020). "Long non-coding RNA nuclear paraspeckle assembly transcript 1 (NEAT1) has been reported to play an essential role in non-alcoholic fatty liver disease." (PMID 33228663, 2020). "As reported, NEAT1 accelerates the accumulation of hepatic lipid in nonalcoholic fatty liver disease via binding to miR-146a-5p to increase ROCK1 expression." (PMID 31868202, 2020). "Previous study showed that NEAT1 knockdown activated AMPK signaling pathway in free fatty acids-treated HepG2 cells, a cell model of nonalcoholic fatty liver disease." (PMID 38684954, 2024).
Obesity (4 papers, 2021 to 2026). Accumulation of substantial excess body fat. "The NEAT1-hsa-miR-204-5p-IGF1 axis may serve as a target for estradiol-leptin synergy in the uterine tissue of patients with obesity and as a biomarker to predict disease." (PMID 36362969, 2022).
oral cancer (4 papers, 2020 to 2025). "The Neat1 SNP has been reported to be associated with the survival of oral cancer patients." (PMID 40027195, 2025). "In a cell culture system, Neat1 expression was shown to be decreased in oral cancer cell lines compared to normal cells." (PMID 40027195, 2025). "Neat1 was markedly downregulated in oral cancer patients from the Taiwanese population." (PMID 40027195, 2025). "Recent evidence now suggests that miR-365 may also function to modulate carcinogenesis and phenotypic behaviors in oral cancers through interactions with nuclear enriched abundant transcript 1 (NEAT1)." (PMID 32727045, 2020). "This study concludes that the NEAT1/miR-125b-5p/SLC1A5 cascade modulates diverse activities in oncogenicity, treatment efficacy, and immune cell profiles in head and neck/oral carcinoma." (PMID 39223142, 2024).
squamous cell carcinoma (4 papers, 2017 to 2024). A carcinoma arising from squamous epithelial cells. "In subtype squamous carcinoma CC patients, minor allele “C” of rs512715 in NEAT1 and minor allele “C” of rs3094 in RNASE4 were associated with increased risk." (PMID 28423658, 2017).
steatosis (4 papers, 2020 to 2024). Increased lipid within the cytoplasm of cells. "Although some LncRNAs, such as MALAT1, H19, and NEAT1, were previously associated with NAFLD, the association of others with steatosis and the positive effect of Ex-4 is being reported for the first time." (PMID 34078383, 2021). "Additionally, NEAT1 was further found to interact with oestrogen receptor α and promoted steatosis in human hepatoblastoma cell line (HepG2) cells." (PMID 39872125, 2024). "Furthermore, NEAT1 could promote steatosis via enhancement of estrogen receptor-mediated AQP7 expression in HepG2 cells." (PMID 34078383, 2021). "ZNF143/NEAT1/SND1-mediated ROCK2 signalling upregulation was associated with the downregulation of mitophagy proteins PTEN-induced kinase 1 (PINK1) and Parkin, suggesting that NEAT1 overexpression may contribute to steatosis by impairing mitochondrial repair mechanisms." (PMID 39872125, 2024). "ZNF143 is a transcription factor for NEAT1, and the upregulation of NEAT1 by ZNF143 exacerbated steatosis." (PMID 39872125, 2024).
anaplastic thyroid carcinoma (3 papers, 2020 to 2022). "In addition to NEAT1, circEIF6 is another ceRNA that bridges autophagy and chemoresistance in anaplastic thyroid carcinomas." (PMID 33050642, 2020). "Increased expression of lncRNA NEAT1 was found in various cancers, such as HCC, anaplastic thyroid carcinoma, and colorectal cancer cells, and was correlated with poor prognosis in these cancers." (PMID 33050642, 2020).
Autoimmunity (3 papers, 2023 to 2025). The occurrence of an immune reaction against the organism's own cells or tissues. "Our study further validated NEAT1s role in dendritic cells which are of critical importance in autoimmunity, and we discovered that NEAT1 could function as the ceRNA to modulate IL-6 secretion via microRNA." (PMID 37343193, 2023). "Here, we reported that Neat1, which was upregulated significantly in CD4+ T cells, was an important regulator of pathogenic Th17 cell responses that contributed to the development of autoimmunity." (PMID 37716986, 2023). "Using the adoptive transfer model of EAU, we further demonstrated that silencing of Neat1 in T cells alone restrained the pathogenic capacity of antigen-specific Th17 cells to induce EAU, highlighting the pivotal role of T cell-intrinsic Neat1 in pathogenic Th17 cell function and autoimmunity." (PMID 37716986, 2023).
endometriosis (3 papers, 2022 to 2025). The growth of functional endometrial tissue in anatomic sites outside the uterine body. "A transcriptomic analysis revealed key miRNAs and lnCRNA implicated in endometriosis and RIF, including miR-9, miR-34, and miR-135a/b miR-30d-5p, PART1, MIR17HG, H19, LINC00173, NEAT1, and LINC01960-201." (PMID 39858500, 2025). "Studies have shown that NEAT1 is significantly up-regulated in endometriosis and promotes malignant behavior in endometriosis by targeting miR-124-3p expression." (PMID 36532015, 2022). "Although some studies have been carried out on the regulation mechanism of NEAT1 and XIST in endometriosis, it still needs to be fully explored in the future, especially in the lncRNA-miRNA-mRNA network." (PMID 36532015, 2022). "In the construction of a ceRNA network composed of four target genes, we found that NEAT1 and XIST have the highest degree of binding to miRNA and may regulate the expression of four genes in endometriosis." (PMID 36532015, 2022). "NEAT1 and XIST may regulate the expression of four TFs (AEBP1, HOXB6, RORB, and KLF2) through the lncRNA-miRNA-mRNA network and participate in the development of endometriosis." (PMID 36532015, 2022).
frontotemporal dementia (3 papers, 2018 to 2020). Frontotemporal dementia (FTD) comprises a group of neurodegenerative disorders, characterized by progressive changes in behavior, executive dysfunction and language impairment, as a result of degeneration of the medial prefrontal and frontoinsular cortices. "Moreover, NEAT1 levels are also increased in the brains of patients affected by frontotemporal lobar degeneration (FTLD)." (PMID 29997370, 2018). "In frontotemporal dementia, NEAT1 interacts with TDP-43, the major protein in FTD inclusion bodies." (PMID 32471155, 2020).
Hantavirus infection (3 papers, 2018 to 2024). "For example, NEAT1 expression is increased during Hantavirus infection, which promotes transcription of immune genes through sequestering of the transcriptionally repressive SFPQ." (PMID 39592606, 2024). "Hantavirus infection also increased the expression of NEAT1 in human umbilical vein endothelial cells." (PMID 30534569, 2018).
hemangioma (3 papers, 2021 to 2024). A benign vascular lesion characterized by the formation of capillary-sized or cavernous vascular channels. "An inverse correlation exists between the expression of lncRNA NEAT1 and miR-361-5p in hemangioma tissues." (PMID 38826780, 2024). "Knockdown of NEAT1 restrains hemangioma endothelial cell proliferation and migration by sequestering miR-361-5p and modulating VEGFA expression." (PMID 38826780, 2024).